PRPF40B (pre-mRNA processing factor 40B)
Description:
May be involved in pre-mRNA splicing.
Synonyms: HYPC
Tractability: PROTAC: UniProt records ubiquitination sites on it; its protein half-life has been measured.
Gene: Protein-coding gene on chromosome 12 (49,568,218 to 49,644,666, forward strand). Ensembl gene ENSG00000110844.
Subcellular location: Nucleus speckle
Subcellular location (Human Protein Atlas): Nuclear bodies; Aggresome; Cytosol; Nucleoplasm
Gene Ontology:
Molecular function: protein binding; RNA binding
Biological process: mRNA splicing, via spliceosome; mRNA cis splicing, via spliceosome
Cellular component: nuclear body; U1 snRNP; U2-type prespliceosome; nuclear lumen; nuclear speck
Genetic constraint (gnomAD): Loss-of-function variants: 52 observed, 120.97 expected, observed/expected ratio (o/e) 0.43, 90% interval 0.34 to 0.54. The upper end of that interval is the gene's LOEUF score, 0.54, which puts it in group 2 of 6, group 1 being the genes least tolerant of losing a copy. Missense variants: 940 observed, 1,118.4 expected, observed/expected ratio (o/e) 0.84, 90% interval 0.8 to 0.89. Synonymous variants: 403 observed, 411.95 expected, observed/expected ratio (o/e) 0.98, 90% interval 0.9 to 1.06.
Homologues: Orthologues: macaque PRPF40B (99% identical), chimpanzee PRPF40B (98% identical), dog PRPF40B (97% identical), guinea pig PRPF40B (97% identical), rat Prpf40b (95% identical), pig PRPF40B (94% identical), mouse Prpf40b (93% identical), rabbit PRPF40B (90% identical), tropical clawed frog prpf40b (66% identical), Drosophila melanogaster Prp40 (39% identical), Caenorhabditis elegans prp-40 (29% identical). Paralogues in human: PRPF40A (57% identical).
Diseases named in the same sentence as PRPF40B in open-access papers:
PRPF40B is named in the same sentence as 13 diseases in open-access papers, as found by Europe PMC text mining. Sharing a sentence is not in itself a finding about the gene and the disease. The quoted sentences say what the papers report.
Rett syndrome (4 papers, 2009 to 2026). A severe neurodevelopmental disorder affecting the central nervous system. "PRPF40B has previously been implicated in the pathogenesis of neurological disorders, including Huntington's disease and Rett syndrome." (PMID 42273035, 2026). "PRPF40B has been implicated in the pathogenesis of various human neurodegenerative diseases and psychiatric disorders, including AD, ALS/FTD, HD, Rett syndrome, and schizophrenia, suggesting an important role for PRPF40B in neuronal development and function." (PMID 41360765, 2025).
cervical cancer (1 paper, 2021). A primary or metastatic malignant neoplasm involving the cervix. "It is displayed in kaplan–Meier curves that higher expression level of EEF1D, CTU1, EIF3C, WDR43, NUFIP1, ZC3HAV1L and PRPF40B indicated a lower overall survival of cervical cancer patients." (PMID 34863153, 2021).
chronic lymphocytic leukemia (1 paper, 2018). "Patients with MDS, chronic myelomonocytoic leukemia (CMML), or chronic lymphocytic leukemia (CLL) acquire mutations in the spliceosomal components SF3B1, SF1, PRPF40B, and U2AF35 besides mutations in the splicing factor SRSF2 and ZRSR2, a component of U11/U12 di-snRNP." (PMID 30246013, 2018).
glioma (1 paper, 2025). A benign or malignant brain and spinal cord tumor that arises from glial cells (astrocytes, oligodendrocytes, ependymal cells). "We also identified PRPF40B, an upstream molecule previously unreported in the context of gliomas, as a regulator of circMAN1A2 expression." (PMID 40583858, 2025). "We found that PRPF40B expression inversely correlated with WHO grade and that lower PRPF40B expression connoted a poor prognosis in glioma patients." (PMID 40583858, 2025).
pancreatic cancer (1 paper, 2015). "A two-stage case-control study was conducted to examine the association between six candidate U2-depedent spliceosome genes (SRSF1, SRSF2, SF3A1, SF3B1, SF1 and PRPF40B) and pancreatic cancer (PC)." (PMID 26498691, 2015).
cancer (2 papers, 2020 to 2023). A tumor composed of atypical neoplastic, often pleomorphic cells that invade other tissues. "The two cancer-related genes, pre-mRNA processing factor 40 homolog B (PRPF40B) and zinc finger homeobox 3 (ZFHX3), were suggested to be potential target mRNAs of lncRNA AC079228.1." (PMID 36819921, 2023).
psychiatric disorder (1 paper, 2025). A disorder characterized by behavioral and/or psychological abnormalities, often accompanied by physical symptoms. "PRPF40B has been associated with various neuronal dysfunctions, including neurodegenerative and psychiatric disorders." (PMID 41360765, 2025).
PRPF40B also shares sentences with these, for which no sentence is quoted: neurological disorders (2 papers); essential tremor (1); Huntington disease (1); myelodysplastic syndrome (1); neurodegenerative disease (1); schizophrenia (1).